CACNA1E (calcium voltage-gated channel subunit alpha1 E)
Diseases named in the same sentence as CACNA1E in open-access papers (continued):
Sharing a sentence is not in itself a finding about the gene and the disease.
Hepatic fibrosis (1 paper, 2025). The presence of excessive fibrous connective tissue in the liver. "Finally, high-impact frameshift mutations in TCF7L2 (VAF = 0.133 in HCC cell line and VAF = 0.024 to 0.094 in HCC tumor regions) and CACNA1E (VAF = 0.089 in HCC tumor) were identified in the hepatic fibrosis pathway." (PMID 40340757, 2025).
metabolic syndrome (1 paper, 2024). A cluster of metabolic risk factors for CARDIOVASCULAR DISEASES and TYPE 2 DIABETES MELLITUS. "Among the genes that exhibit interaction with CACNA1E, the SLC12A2 gene, which encodes the solute carrier family 12 (sodium/potassium/chloride transporter) member 2, has been recently associated to metabolic syndrome in mice." (PMID 39273144, 2024).
myocardial infarction (1 paper, 2022). Gross necrosis of the myocardium, as a result of interruption of the blood supply to the area, as in coronary thrombosis. "Based on the available information and our study results, we hypothesized that CACNA1E is differentially expressed during an inflammatory response, thereby affecting the serious outcomes of KD such as CALs and even CAA dilation, stenosis, thrombosis, and myocardial infarction." (PMID 36042431, 2022).
Neurodevelopmental delay (1 paper, 2023). "The overlap in clinical manifestations between CACNA1E and CDD patients, including seizures and neurodevelopmental delays, raises the possibility that Cav2.3 regulation by CDKL5 might affect channel function and in turn neuronal excitability." (PMID 38081835, 2023).
non-small cell lung carcinoma (1 paper, 2024). A group of at least three distinct histological types of lung cancer, including non-small cell squamous cell carcinoma, adenocarcinoma, and large cell carcinoma. "CACNA1E encodes a calcium voltage-gated channel subunit alpha-1 E, which was hypothesized to act as an oncoprotein in non-small cell lung cancer, required for cell proliferation." (PMID 39208653, 2024).
paraganglioma (1 paper, 2022). A benign or malignant neoplasm arising from paraganglia located along the sympathetic or parasympathetic nerves. "Lower expression levels of CACNA1E were found in pheochromocytoma, paraganglioma (PCPG), kidney renal clear cell carcinoma (KIRC), and sarcoma (SARC)." (PMID 35571016, 2022).
situs inversus (1 paper, 2022). A congenital condition in which there is complete right-to-left reversal of the position of the major thoracic and abdominal organs (that is, they are arranged in a mirror image of the normal positioning). "In 13 interrupted genes, CACNA1E (in case 12) and STARD7 (in case 17) are known causative and PDCL was found in subject (case 11) with situs inversus for the first time." (PMID 36186435, 2022).
tumor (8 papers, 2018 to 2025). "CACNA1E, the voltage-gated calcium channels (VGCCs) family member, often mediates the tumor evolution and heterogeneity formation via MAPK signaling pathway." (PMID 33816287, 2021). "The correlation analysis in our study showed that LumB- is characterized by the methylation of two genes—PRDM14 and CACNA1E—which could be considered a potential prognostic marker of tumor progression." (PMID 37628841, 2023). "Correlation analysis showed that the methylation of the PRDM14, CACNA1E, CCDC181, and GCM2 genes correlated with tumor size." (PMID 37628841, 2023). "In our study, we used a set of 96 tumor samples of less than 2 cm; in this set, the assessment of the methylation of the GCM2, ITPRIPL1, CACNA1E, and DLGAP2 genes most accurately distinguished cancer from healthy tissues." (PMID 37628841, 2023). "The level of methylation in four genes—PRDM14, CACNA1E, CCDC181, and GCM2—correlated with tumor size." (PMID 37628841, 2023). "VCGG channels, including CACNA1C, CACNA1D, CACNA1F, CACNA1E, CACNA1A, CACNA1G, CACNA1I, showed significantly higher expression in KIRC than normal cases, whereas CACNA1S and CACNA1H showed higher expression in normal than tumor cases." (PMID 36588677, 2022).
cancer (7 papers, 2016 to 2025). A tumor composed of atypical neoplastic, often pleomorphic cells that invade other tissues. "In addition, SNVs were detected in genes that were previously associated with cancer, such as CACNA1E, PRKD1, NDST4, and were also considered pathogenic/deleterious/not tolerated in at least three mutation function models." (PMID 29854292, 2018). "The main pathways of methylome biomarkers were associated with calcium signalling (CACNA1E, RYR2, RYR3), cancer pathways (DCC, RASSF1, WNT1, CTNNA2), multiple neurodegenerative diseases (WNT1, DNAI1, RYR2, RYR3), immune system disorders and cell adhesion (HLA-DRA, HLA-DRB1, HLA-DRB5)." (PMID 40524349, 2025). "All these data indicate that CACNA1E is probably a cancer driver in BC for young women." (PMID 39208653, 2024). "Furthermore, pan-cancer analysis of the hub genes revealed three genes, namely, CACNA1E, DDN, and SH3GL2, which were predominantly downregulated in GBM but not identified in more than five cancer types, could also make them putative prognostic biomarkers for GBM." (PMID 35571016, 2022). "Moreover, we found two key TFs (EPO, ARID3A), four key PRSGs (CACNA1E, LINC01356, CGA and SSX3) and five key hallmarks of cancer gene sets (DNA repair, myc targets, E2F targets, mTORC1 signaling and unfolded protein response) in the regulatory network." (PMID 33816287, 2021). "Furthermore, the most diversely expressed genes were particularly enriched in MAPK signaling pathway, such as CACNG4, CACNA1E and CACNA1H, which involve in cancer evolution and heterogeneity formation." (PMID 27602771, 2016). "Besides that, some affected new potential cancer drivers (genes that were not cataloged at CGC) were identified, such as CACNA1E, GRHL2, MTHFD2, PIK3AP1, RSBN1, SEMA6D, and SMURF2." (PMID 39208653, 2024).
neurodevelopmental disorder (5 papers, 2019 to 2026). A behavioral and cognitive disorder with onset during the developmental period that involves impaired or aberrant development of intellectual, motor, or social functions. "This cohort has enabled us to broaden the genotypic and the phenotypic spectrum of CACNA1E-related neurodevelopmental disorder." (PMID 34702355, 2021). "The CACNA1E gene was also identified as a candidate gene for neurodevelopmental disorders." (PMID 32466254, 2020). "While we did not observe exome-wide significant enrichment of damaging DNMs in these genes, partly due to limited availability of the DNA samples of the parents, we confirmed that two CD missense URVs in CACNA1E, a gene recently reported as a EE/DEE/neurodevelopmental disorder gene, are DNMs." (PMID 31175295, 2019).
cardiovascular disease (1 paper, 2014). "The 155 - 157 Mb interval is syntenic with Chr1q25, where an intron SNP marker in RGS8 is associated with cardiovascular disease (8.9) and SNPs near and within the CACNA1E gene are associated with HDL cholesterol levels (9.5), echocardiography (5.2) and blood pressures (4.9)." (PMID 24586312, 2014).
infectious disease (1 paper, 2023). A disorder directly resulting from the presence and activity of a microbial, viral, or parasitic agent in humans. "Only three genes overlap between the three studies, with CACNA1E being overexpressed, whereas CD28 and PCED1B had lower expression levels in patients with infectious disease." (PMID 37108169, 2023).
CACNA1E also shares sentences with these, for which no sentence is quoted: neurological disorders (3 papers); Anxiety (2); movement disorder (2); Pain (2); Parkinson’s (2); type 1 diabetes (2); Anorexia (1); autism spectrum disorder (1); cerebellar ataxia (1); Cerebellar atrophy (1); Cognitive impairment (1); colitis (1); COVID-19 (1); dental caries (1); Dystonia (1); Fibroadenoma (1); glioma (1); heart diseases (1); heart failure (1); hypercalcaemia (1); Hypotonia (1); immune system disorder (1); infantile epileptic encephalopathy (1); Insulin resistance (1); insulinoma (1); ischemia (1); left ventricular hypertrophy (1); liver cancer (1); lung carcinoma (1); lung squamous cell carcinoma (1).
A further 15 diseases each share a sentence with CACNA1E in 1 paper.